RNU5D-1 (RNA, U5D small nuclear 1)
Synonyms: U5DS; U5DL; RNU5D
Gene: Small nuclear RNA gene on chromosome 1 (44,731,069 to 44,731,170, reverse strand). Ensembl gene ENSG00000200169.
Gene Ontology:
Biological process: formation of quadruple SL/U4/U5/U6 snRNP; spliceosomal tri-snRNP complex assembly
Cellular component: U4/U6 x U5 tri-snRNP complex; U5 snRNP